NFKB2 (nuclear factor kappa B subunit 2)
Diseases named in the same sentence as NFKB2 in open-access papers (continued):
Sharing a sentence is not in itself a finding about the gene and the disease.
gastric cancer (6 papers, 2020 to 2025). A primary or metastatic malignant neoplasm involving the stomach. "A recent investigation has revealed that the expression of five genes linked to the cGAS-STING pathway, namely IFNB1, IFNA4, IL6, NFKB2, and TRIM25, exhibits potential as a valuable prognostic marker for OS in patients suffering from gastric cancer." (PMID 38240703, 2024). "The Kaplan‒Meier plotter online website showed that gastric cancer patients with high NFKB2 expression had a poor prognosis, and the difference was statistically significant compared with patients with low NFKB2 expression (P <0.01)." (PMID 38577985, 2024). "NFKB2 has been observed to be upregulated in gastric cancer tissues, and its altered expression can collaborate with heterozygous KrasMUT to drive tumorigenesis but decreases the metastatic potential of pancreatic ductal adenocarcinoma." (PMID 33042984, 2020). "However, in the case of gastric cancer, in silico studies using the TIMER database showed a positive correlation between NFKB2 and BAX gene expression (r = 0.341; p < 0.001)." (PMID 41614769, 2025). "Recently, it has been demonstrated that the relative expression level of nuclear factor kappa B subunit 2 (NFκB2) gene is decreased in gastric cancer as opposed to PUD which might suggest the inhibition of the NF-κB pathway during carcinogenesis." (PMID 35056399, 2022).
lymphoma (5 papers, 2010 to 2023). A malignant (clonal) proliferation of B- lymphocytes or T- lymphocytes which involves the lymph nodes, bone marrow and/or extranodal sites. "If Myc-mediated reductions in Nfkb2 expression in Eμ-Myc B cells were important for Myc-mediated lymphomagenesis, we reasoned that total loss of Nfkb2 should affect lymphoma development." (PMID 20598117, 2010). "The contribution of Nfkb2 to Myc-driven lymphomagenesis was tested in vivo, where Nfkb2 loss was shown to accelerate lymphoma development in Eμ-Myc transgenic mice, by impairing Myc's apoptotic response." (PMID 20598117, 2010). "NFKB2 deficiency can accelerate the development of lymphoma in Eμ‐myc transgenic mice." (PMID 36323529, 2023). "Lastly, expansion of four B-cell subpopulations in the analyzed subjects prompted us to check whether a nonsense mutation at a similar location in NFKB2 was reported in lymphomas." (PMID 30863427, 2019). "Besides NFKB2 nonsense mutations detected in lymphomas, there is also a report of p.Arg609∗ mutation that was found in thyroid carcinoma." (PMID 30863427, 2019). "Thus, the accelerated lymphoma development manifest in Eμ-Myc;Nfkb2-/- mice is associated with an impaired apoptotic response." (PMID 20598117, 2010). "NFKB2 is also a MYC repression target and Nfkb2 loss has been shown to accelerate lymphoma development in Eμ-Myc transgenic mice." (PMID 23828858, 2013). "Further, there was a marked suppression of Nfkb2 transcripts in all Eμ-Myc lymphomas, and in all human Burkitt lymphomas compared to pooled CD19+ control B cells from healthy donors." (PMID 20598117, 2010). "Precancerous Eμ-Myc-transgenic B cells, Eμ-Myc lymphomas and human Burkitt lymphoma samples were assessed for Nfkb2 expression." (PMID 20598117, 2010). "The lymphomas that arose in Eμ-Myc;Nfkb2-/- transgenics were phenotypically identical to those that arose in Eμ-Myc;Nfkb2+/+ mice, and full necropsy and histopathological examination demonstrated similar dissemination of disease in Eμ-Myc;Nfkb2+/+ versus Eμ-Myc;Nfkb2-/- mice (data not shown)." (PMID 20598117, 2010). "Importantly, Eμ-Myc;Nfkb2-/- transgenic displayed a moderately accelerated course of lymphoma development and, accordingly, had a shorter lifespan, with a median survival of 171 days compared to 205 days median survival in their Eμ-Myc;Nfkb2+/+ littermates (p = 0.0307)." (PMID 20598117, 2010). "Thus, Nfkb2 expression is suppressed in Myc-driven lymphomas in mice and man." (PMID 20598117, 2010).
prostate carcinoma (5 papers, 2017 to 2020). A carcinoma that arises from epithelial cells of the prostate gland. "NFKB2, which is involved in aberrant activation of androgen receptor in prostate cancer cells, might be coregulated by FXR2 and HNRNPA1 proteins based on our motif enrichment analysis." (PMID 32316190, 2020). "NFKB1 (nuclear factor-κB subunit 1) and NFKB2 (nuclear factor-κB subunit 2) gene expression was up-regulated by Ang1–7 in all prostate cancer cells, but this increase was not statistically significant for the DU-145 line." (PMID 30361641, 2018).
rheumatoid arthritis (5 papers, 2016 to 2022). A chronic, systemic autoimmune disorder characterized by inflammation in the synovial membranes and articular surfaces. "In particular, NFKB2 was predicted to be a target of sulfasalizine used for the treatment of rheumatoid arthritis and was validated in TTD46." (PMID 26853265, 2016).
glioma (4 papers, 2021 to 2024). A benign or malignant brain and spinal cord tumor that arises from glial cells (astrocytes, oligodendrocytes, ependymal cells). "To functionally validate the role of p52-activated ETS1 in glioma progression, we targeted NFKB2 and ETS1 expression in U-87 MG and U-251 MG cells using CRISPR-Cas9 gene editing tools and verified their downregulation through western blotting." (PMID 37087499, 2023). "The Pearson correlation analysis indicated that strong positive correlations occurred between CHI3L1 and ACTN4, NFKB1 or NFKB2 in TCGA and CGGA glioma cohorts." (PMID 36276655, 2022).
influenza (4 papers, 2013 to 2022). An acute viral infection of the respiratory tract, occurring in isolated cases, in epidemics, or in pandemics; it is caused by serologically different strains of viruses (influenzaviruses) designated A, B, and C, has a 3-day incubation period, and usually lasts for 3 to 10 days. "Activation of the non-canonical NF-κB/NFKB2 pathway has never been reported in cytokine storms caused by other respiratory viruses such as influenza." (PMID 36380355, 2022). "Activation of the non-canonical NF-κB/NFKB2 pathway was never reported in the cytokine storms caused by other respiratory viruses such as influenza; thus, this finding provided a unique insight to the pathogenesis of SARS-CoV-2." (PMID 33060566, 2020).
leukemia (4 papers, 2011 to 2025). A malignant (clonal) hematologic disorder, involving hematopoietic stem cells and characterized by the presence of primitive or atypical myeloid or lymphoid cells in the bone marrow and the blood. "In agreement with this hypothesis, several of the genes identified in our analysis have been suggested to be putative therapeutic targets in leukemia, with either preclinical or clinical trials underway (CDK4, CDK6, GSK3b, MYC, LCK, NFkB2, BCL2L1, NOTCH1)." (PMID 21356087, 2011). "Previously, we found that TKI-treatment could activate a non-canonical NFKB2/Cytokines/Chemokines/CXCR2 pro-leukemia inflammatory pathway to initiate the survival and relapse of FLT3-mut AML blasts ex vivo." (PMID 38023123, 2023).
lung carcinoma (4 papers, 2018 to 2022). "In addition, ATF3 decreases nuclear factor kappa B subunit 2 (NFKB2) expression and reverses drug resistance in lung cancer cells." (PMID 36123698, 2022).
melanoma (4 papers, 2015 to 2022). A malignant, usually aggressive tumor composed of atypical, neoplastic melanocytes. "We previously reported that BET inhibitors repressed melanoma progression through the nuclear factor kappa B subunit 2 (NFKB2)/SPP1 pathway." (PMID 35184394, 2022). "Among the critical regulons in neoplastic cells with high PTX3 expression, NFKB2 was recently found to mediate melanoma progression." (PMID 35855654, 2022). "Also, siRNA-mediated down-regulation of NFKB2 resulted in reduced melanoma cell proliferation, migration, and invasion." (PMID 33052224, 2020). "Mechanistically, BET inhibitors suppressed melanoma progression via the BRD4/NFKB2/SPP1 axis." (PMID 33052224, 2020). "Silencing of NFKB2 resembled the phenotype of BET inhibitors treatment and SPP1 silencing in melanoma." (PMID 33052224, 2020). "We found that small interfering RNA-mediated down-regulation of NFKB2 impaired the proliferation, migration and invasion abilities, which mimicked the phenotype of BET inhibitor treatment and SPP1 silencing in melanoma." (PMID 33052224, 2020). "NFKB2 is a member of the noncanonical NF-κB signaling pathway and its role in melanoma was not clarified previously." (PMID 33052224, 2020). "Our study found that BRD4 silencing in A375 melanoma cells did not affect the expression of transcriptional factors in the canonical NF-κB pathway but affected NFKB2 expression in the noncanonical NF-κB pathway." (PMID 33052224, 2020). "NFKB2 silencing resembled the phenotype observed by BET inhibitors and SPP1 silencing in melanoma." (PMID 33052224, 2020).
multiple myeloma (4 papers, 2008 to 2024). "To further characterise the p52-dependent transcriptional programmes active in NF-κB+ multiple myeloma, we disrupted the constitutive expression of p52 in several NF-κB+ Multiple Myeloma cell lines (MMCL) by targeting the Rel Homology Domain (RHD) of the NFKB2 gene (NFKB2 KD)." (PMID 38514625, 2024).
autoimmune disease (3 papers, 2019 to 2022). A disorder resulting from loss of function or tissue destruction of an organ or multiple organs, arising from humoral or cellular immune responses of the individual to their own tissue constituents. "Thus, NFKB2 was previously genetically associated with pleiotropic autoimmune diseases, in the context of CVID." (PMID 30696696, 2019). "On the other hand, NFKB2−/− mice are affected by thymic medullary hypoplasia and autoimmune diseases." (PMID 36555871, 2022). "Therefore, damaging NFKB2 mutations cause a more severe form of PID with early-onset and a distinct, multifaceted auto-immunity with primarily T cell mediated autoimmune diseases, such as alopecia, lymphocytic organ infiltration, and possibly ACTH-deficiency." (PMID 30941118, 2019).
colitis (3 papers, 2015 to 2024). Inflammation of the colon. "The response of Nfkb2−/− mice to DSS colitis was also strikingly less severe than that of mice of other genotypes." (PMID 25727407, 2015). "To investigate the effect of NF‐κB subunit loss on colitis‐associated carcinogenesis, we administered azoxymethane followed by pulsed dextran sodium sulphate to C57BL/6, Nfkb1−/−, Nfkb2−/−, and c‐Rel−/−mice." (PMID 25727407, 2015). "Because of the shared colitis resilience phenotype of Relb∆CD11c and Nkfb2∆CD11c mice, we focused on Raldh2, whose expression was similarly affected upon ablation of either Relb or Nfkb2 in BMDCs." (PMID 39060515, 2024). "Taken together, we deduce that a DC-intrinsic RelB function, where Nfkb2 is dispensable, limits the accumulation of intestinal IgA+ B cells and luminal IgA, which likely foster a gut microbiome protective against experimental colitis in mice." (PMID 39060515, 2024). "When transgenic mice lacking specific NF-κB subunits were subjected to dextran sulphate sodium (DSS) treatment in a model of colitis, mice lacking cRel and Nfkb1 developed more severe colitis than wild-type controls, whereas Nfkb2−/− mice were resistant to colitis." (PMID 32958515, 2020). "Hence Nfkb2−/− animals subjected to DSS and AOM were protected from developing colitis‐associated colonic neoplasia primarily by an attenuated inflammatory response." (PMID 25727407, 2015). "To address this, we have studied the effects of DSS/AOM‐induced colitis‐associated carcinogenesis in mice carrying germline deletions of the Nfkb1, Nfkb2 or c‐Rel genes and have also investigated the impact of these deletions on DSS‐induced colitis and colonic responses to DNA damage." (PMID 25727407, 2015).
diabetes (3 papers, 2024 to 2025). "Another study investigating differential monocyte gene expression in individuals with diabetes identified IRF1, GATA6, SP11, EPAS1, NFKB2, and STATB3 as key affected transcription factors." (PMID 40476695, 2025). "Key examples include IRF1, GATA6, SPI1, EPAS1, NFKB2, and STAT5B, which are involved in immune response, cell differentiation, and metabolic regulation, all of which are critical in diabetes pathogenesis." (PMID 39877357, 2024).
liver disease (3 papers, 2020 to 2025). "Overall, the upregulation of CDKN1A, NFKB2, RELB, and PDIA3 indicates a worse prognosis of liver disease and an impaired immune response against HIV." (PMID 33785040, 2021). "We also describe the clinical features of liver disease in some monogenic forms of PID included in the clinical spectrum of CVID as ICOS, NFKB1, NFKB2, CTLA-4, PI3Kδ pathway, ADA2, and IL21-R genetic defects." (PMID 32184784, 2020).
ovarian carcinoma (3 papers, 2014 to 2022). A malignant neoplasm originating from the surface ovarian epithelium. "Elevated expression of NFKB2/p52 prompted us to examine NIK expression in ovarian cancer cells." (PMID 24533079, 2014).
Primary Immunodeficiency (3 papers, 2019 to 2025). "Here, we investigate 15 previously unreported patients with primary immunodeficiency (PID) from eleven unrelated families with heterozygous NFKB2-mutations including eight patients with the common p.Arg853* nonsense mutation and five patients harboring unique novel C-terminal truncating mutations." (PMID 30941118, 2019). "We assessed hormone levels, performed provocative tests and genetic testing in a subset of patients by direct sequencing of the nuclear factor kappa beta subunit 2 (NFKB2) gene and primary immunodeficiency (PID) gene panel testing by whole exome sequencing (WES)." (PMID 31543881, 2019).
psoriasis (3 papers, 2015 to 2019). An autoimmune condition characterized by red, well-delineated plaques with silvery scales that are usually on the extensor surfaces and scalp. "NFKB2's targets are enriched in the phenotype “chronic inflammatory diseases (ankylosing spondylitis, Crohn's disease, psoriasis, primary sclerosing cholangitis, ulcerative colitis) (pleiotropy)”." (PMID 30696696, 2019). "Contrary to our hypothesis, deficiency in Map3k14 or Nfkb2 did not prevent the psoriasis-like skin disease in Traf2EKO mice." (PMID 26701909, 2015).
Sepsis (3 papers, 2023 to 2024). Sepsis is defined as life-threatening organ dysfunction caused by a dysregulated host response to infection. "NF-κB transcription factor family members, including RELB, NFKB2, REL, and IRF1, predominantly control WARS1-induced gene expression networks, indicating recapitulating hyperinflammatory sepsis endotypes." (PMID 38177528, 2024). "Collectively, these results pinpoint NFKBIA, NFKB2, TNFSF14, DUSP2, and PIK3C2B as key mediators of DcR3’s broad-spectrum effects in CLP-induced sepsis." (PMID 38700314, 2024). "Genes that participate in this pathway and were differentially expressed in our sepsis patients include PSMB1, NFKB2, SEM1, UBB and RELA." (PMID 37731199, 2023).
Stroke (3 papers, 2018 to 2025). Sudden impairment of blood flow to a part of the brain due to occlusion or rupture of an artery to the brain. "After a stroke, RNA sequencing showed an increase in genes associated with the TREM-1 and NLRP3 pathways, including Nfkb2 and IL-1β, which contribute to the neuroinflammatory response immediately after ischemia." (PMID 40867169, 2025). "Other examples include CASP8 with cancer, NFKB2 with IBD, and DLG4 with stroke." (PMID 33990562, 2021). "Tnfrsf1a, Tnfrsf1b, and Nfkb2 are known to be involved in inflammatory responses to stroke via noncanonical I-kappa B kinase/NF-kappa B cascade." (PMID 29516010, 2018).
B cell deficiency (2 papers, 2014 to 2019). A broad classification of disorders where circulating numbers of B lymphocytes are decreased or ineffective. "Patients with heterozygous mutations in NFKB2/p100 have recently been described with B-cell deficiency and autoimmunity." (PMID 25406581, 2014).
Burkitt lymphoma (2 papers, 2010 to 2023). A rare form of malignant mature B-cell non-Hodgkin lymphoma. "Here we report that the Myc oncoprotein suppresses Nfkb2 expression in vitro in primary mouse fibroblasts and B cells, and in vivo in the Eμ-Myc transgenic mouse model of human Burkitt lymphoma (BL)." (PMID 20598117, 2010).
chronic granulomatous disease (2 papers, 2021 to 2025). Chronic granulomatous disease (CGD) is a rare primary immunodeficiency, mainly affecting phagocytes, which is characterized by an increased susceptibility to severe and recurrent bacterial and fungal infections, along with the development of granulomas. "Among patients treated in the ICU settings there were patients with a diagnosis of chronic granulomatous disease (n = 1), trisomy 21 (n = 1), Wiskott-Aldrich syndrome (n = 1), nuclear factor κB mutation (NFKB2) (n = 1) and X-linked inhibitor of apoptosis protein (XIAP) deficiency (n = 1)." (PMID 34768630, 2021).
clear renal cell carcinoma (2 papers, 2021 to 2024). "Out of 21 cancer types, the analysis revealed that the higher the NFKB2 mRNA expressed, the lower the survival time for patients with renal clear cell carcinoma compared with patients with low NFKB2 expression." (PMID 39062057, 2024).
colorectal cancer (2 papers, 2024). A primary or metastatic malignant neoplasm that affects the colon or rectum. "This study systematically analyzed the molecular mechanism and function of nuclear factor kappa B subunit 2 (NFKB2) in colorectal cancer (CRC) to investigate the potential of NFKB2 as a therapeutic target for CRC." (PMID 38660687, 2024). "The relationship between nuclear factor kappa B subunit 2 (NFKB2) expression and clinicopathological features of patients with colorectal cancer." (PMID 38660687, 2024). "We found that the most significant drivers of the differences between left-sided and right-sided colorectal cancer found in our analysis are ZNF350 (t-test, FDR = 0.024) and NFKB2 (t-test, FDR = 0.032) respectively." (PMID 38438786, 2024).
Crohn disease (2 papers, 2019 to 2025). A gastrointestinal disorder characterized by chronic inflammation involving all layers of the intestinal wall, noncaseating granulomas affecting the intestinal wall and regional lymph nodes, and transmural fibrosis. "For example, TLR7, NFKBIA, NFKBIZ, NFKB2, and TNFRSF19 have been shown to be upregulated in epithelial cells and macrophages during infection with AIEC strains isolated from Crohn’s disease patients." (PMID 40572318, 2025).
Cutaneous T cell lymphoma (2 papers, 2008 to 2019). "Chromosomal translocations disrupting the Nfkb2 gene that generate truncated p100 proteins and constitutive processing of p100 to p52 were identified in cutaneous T-cell lymphoma, and, more rarely, in B-cell non-Hodgkin lymphoma, chronic lymphocytic leukemia, and multiple myeloma." (PMID 18596915, 2008).
diffuse large B-cell lymphoma (2 papers, 2022). "In malignancy processes, it was noted that the activation of either NFKB1 or NFKB2 is associated with different phenotypes of cancer, namely in diffuse large B-cell lymphoma (DLBCL)." (PMID 36555871, 2022). "In the first study, a gene homologous to the REL transcription factors, later designated as NFKB2, was cloned from a translocation breakpoint in a diffuse large B-cell lymphoma (DLBCL) case." (PMID 36289712, 2022).
ectodermal dysplasia (2 papers, 2019). "Intriguingly, patients with overactive NFKB2, responsible for the so-called noncanonical NF-κB pathway, may develop ectodermal dysplasia, a feature typical for XLPDR, as well as adrenal insufficiency, which is a feature of the MCM4 deficiency phenotype." (PMID 31672938, 2019).
eosinophilia (2 papers, 2022). "The numbers of patients varied by condition, for example, while NFKB2 was associated with the highest proportion of patients with eosinophilia (100%), there were only 3 patients with this condition included in our analysis." (PMID 35273610, 2022). "Within these IEIs, the proportion of patients with eosinophilia ranged from 8.5 to 100%, with the highest proportion identified in NFKB2." (PMID 35273610, 2022).